IL2 (interleukin 2)
Diseases named in the same sentence as IL2 in open-access papers (continued):
Sharing a sentence is not in itself a finding about the gene and the disease.
viral infection (continued). "JNK signaling pathway was suggested to play a prominent role in immune response to viral infection due to activation of several interleukins (IL-2, IL-4) and IFN-γ." (PMID 35213582, 2022). "Our data demonstrate a clear increase in IFN-γ in relation to other cytokines (IL-2 and IL-4) in the brain of surviving animals, corroborating the contribution of this cytokine to viral infection control and protection." (PMID 36679918, 2022). "SARS-CoV-2-specific CD4+ Th1 cells that produce IFNγ, TNF-ɑ, and/or IL-2 can be detected in vaccinators or convalescents, which is similar to other viral infections." (PMID 36032096, 2022). "Previous research revealed that androgen inhibits murine and human CD4 T cells differentiated into T-helper 1 cells by blocking IL-2 signaling, providing solid evidence for targeting androgen in rescuing immune responses in confronting virus infection." (PMID 36119091, 2022). "In response to most viral infections, B cells can bind to viral proteins through their antigen receptors, by secreting effector molecules (IL-2, IL-4, IL-6, IFN-γ, TNF-α) to help contain viral infections." (PMID 35774402, 2022). "Recently, clinical trials utilizing bisphosphonates, such as PAM and ZOL, to expand γδ-T cell in vivo in combination with IL-2 therapy or adoptive transfer of ex vivo cultured γδ-T cells were performed in patients with tumors and virus infections." (PMID 35784354, 2022). "The activation of NF-κB in viral infection induces gene expression of a wide range of cytokines (e.g., IL-1, IL-2, IL-6, IL-12, TNF-α, LT-α, LT-β, and GM-CSF), and chemokines (e.g., IL-8, MIP-1, MCP1, RANTES, and eotaxin)." (PMID 35967323, 2022). "Cytotoxic effector genes (GZMA, GZMB, ID2, and PLAC8) were enriched in Δ382 SARS-CoV-2 infected patients, coupled with high plasma levels of IFN-γ, TNF-α, and IL-2 during the acute phase of virus infection." (PMID 34716845, 2022). "In the absence of ex vivo stimulation, IL-2 production by naive Foxp3− CD4+ T cells was also observed in early life after viral infection, and IL-2+ cells expressed more IL-2 per cell than those from adults." (PMID 34665220, 2021). "Namely, JNKs are important kinases that are activated in innate immune responses to viral infection and stimulate the activity of several significant cytokines, including interleukins (IL-2, IL-4)." (PMID 34988113, 2021). "Splenocytes and TDLN cells from mRIPO-treated mice secreted higher IFN-γ, IL-2, and other cytokines at baseline, indicating systemic bystander effects of intratumor viral infection/ replication." (PMID 33767151, 2021). "Th1 cells, which produce cytokines such as IFN-γ, tumor necrosis factor alpha (TNF-α), and interleukin (IL)-2, play an important role in protection against viral infection." (PMID 33688034, 2021). "Together, these data showed that both IFN-γ and IL-2 signaling suppress IgG1 responses during early-life viral infection, with IFN-γ broadly limiting immune responses and IL-2 appearing to specifically attenuate the formation of TFH and GC B cells." (PMID 34665220, 2021). "The previous study provided evidence that CREM prevents production of IL-2 during chronic viral infection, thereby contributing to T-cell exhaustion." (PMID 34938728, 2021). "During a chronic viral infection or under IL-2-deprived conditions IL-21R signaling is critical for preventing CD8+ T-cell exhaustion." (PMID 34721405, 2021). "We, however, find enhanced Il2 expression in the LNs of neonatal mice after viral infection compared with adults." (PMID 34665220, 2021). "This is in keeping with works showing that during a chronic viral infection or under IL-2-deprived conditions, IL-21R signaling is critical for preventing CD8+ T-cell exhaustion." (PMID 34721405, 2021).
viral infection (continued). "After a long-lasting viral infection, IL-2 secretion and the ability to lyse target cells are the first CD8+ T cell functions deleted, followed by the suppression of tumour necrosis factor (TNF)α and IFNγ secretion and a subsequent final deletion of T cells." (PMID 33802622, 2021). "During the early stage of viral infection, cytokines (IL-1, IL-2, IL-8, IL-10, CCL2, CCL7, IFN-α, IFN-β, and TNF-α) have essential functions in the recruitment of immune cells, defense against the infection, and promotion of inflammation." (PMID 34603560, 2021). "To verify the observation in the human study, we further investigated the immunoregulatory function of Ld-IL2 therapy using multiple mouse models of viral infection to determine its benefits and potential adverse effects." (PMID 34618873, 2021). "These suggest that IL-2-enhanced the generation of effector CD8+ T cell response that controlled viral infection in mice, providing a rationale of why Ld-IL2 treatment sustains anti-viral immunity in SLE patients." (PMID 34618873, 2021). "The association study of SLE patients suggested a beneficial role of Ld-IL2 therapy in controlling viral infection." (PMID 34618873, 2021). "In summary, Ld-IL2 therapy reduced the risk of infections in SLE patients and enhanced the control of viral infection, but caution should be taken to avoid potential CD8+ T cell-mediated immunopathology." (PMID 34618873, 2021). "There were 14 trials (participants = 2329) that used cytokines such as IL-2 and IL-7 for lymphocyte activation or type I IFNs to induce innate immunity against virus infections." (PMID 34959492, 2021). "NK cells are an important effector of the innate immune system, and when activated by IL-2, the function of NK cells, such as protection against tumor cells and viral infections, is enhanced." (PMID 33266362, 2020). "The expression level of IL-2 in the body is significantly increased during viral infection, which can rapidly and extremely drive the inflammation of the BF." (PMID 33553290, 2020). "A preferential reconstitution and expansion of NK cells expressing the inhibitory receptor Ly49G2 after HSCT, viral infection or IL-2 stimulation has been previously reported by our group." (PMID 33138229, 2020). "Multifunctional T cells, simultaneously secreting IL-2, TNF-α, and IFN-γ, have been associated with the control of numerous viral infections, including HCV." (PMID 33343515, 2020). "The role of IL-2 and IL-4 is to resist viral infection, activate T cells, promote B cell proliferation, and secrete antibodies." (PMID 33390949, 2020). "Among CD56+ cells, 10% are CD56bright cells, which are known for having critical importance in contributing to cytokine production in viral infections, specifically through the production of IL-1, IL-2, and IL-18." (PMID 30944834, 2019). "Upon a mucosal viral infection in vivo, recruited inflammatory immune cells secrete IL-2 in the inflamed tissue." (PMID 30651370, 2019). "The peak of CD4+IL-2+ responses following KOS infection on day 14 PI was greater than responses to D22 (ICP22 null) virus infection (79.4% vs. 64.5%, P < 0.01) and was reduced on day 28 PI (60.5% vs. 36.2%, P < 0.001)." (PMID 31387116, 2019). "In dengue infection, one study showed that CD4+ T cells that produced either IFNγ or IL-2 correlated with protection from secondary virus infection in children." (PMID 30761131, 2019). "During acute viral infection, the interleukin-2 (IL-2)-mTORC1 signaling axis orchestrates the reciprocal balance between Th1 and Tfh cell fates by promoting Th1 while inhibiting Tfh cell differentiation." (PMID 30828337, 2019). "Since T cells with increased IL-2R expression are also upregulated in patients with viral infections, we advise to exclude patients with a possible viral infection before performing radiolabelled IL-2 imaging, to increase specificity." (PMID 31076906, 2019).
viral infection (continued). "Overall, our results indicate that memory CD4 T cell-derived IL-2 acts as a potent adjuvant in the lung that enhances the production of a broad early inflammatory response during acute viral infection." (PMID 31412088, 2019). "A large body of literature documents that the magnitude of the CD8 T cell response during persistent viral infections is regulated, in part, by IL-21 and IL-2 produced by CD4 T cells." (PMID 30372487, 2018). "IL-2 and IL-6 were also found to be significantly up-regulated in other viral infections in the duck, such as in infections with AIV, DTMUV, and DEV." (PMID 29925406, 2018). "The reports that IL-2 can expand and induce Treg cells in vivo and in vitro, are in line with our present study showing that depletion of FoxP3-expressing cells blocked CNS demyelination by HSV-IL-2 and required both IL-2 and viral infection." (PMID 28542613, 2017). "Viral infection and interleukin-2 promote the differentiation of Id3hi into Id3lo Treg cells and during chronic infection Id3lo Treg cells are the predominant Treg cell population." (PMID 29262527, 2017). "In response to virus infection, CD44highGFP-Egr2high and CD44highGFP-Egr2low T cells produced IL2 and effector cytokines differentially, again similar to T cells from CD2-Egr2 transgenic and CD2-Egr2/3−/− mice." (PMID 28487311, 2017). "IL-2 is known to be an important cytokine produced by activated T cells for controlling viral infection." (PMID 29257056, 2017). "TH1 cells mainly produce IFN-γ, IL-2, and IL-12 and play a critical role in cell-mediated immune responses and therefore the clearance of viral infection; TH1 polarization is essential for the protective activity against influenza." (PMID 27376063, 2016). "While this intervention was highly effective, IL-2 Ab Cx was injected prophylactically prior to virus infection." (PMID 27886209, 2016). "We show that active virus infection can change the response pattern of IL-2 Ab Cx, resulting in the expansion of pro-inflammatory rather than anti-inflammatory T cells, cautioning its use as a therapeutic agent." (PMID 27886209, 2016). "The significant increase in CD25+ Teffs in the footpad of CHIKV-infected mice suggests that exposure to IL-2 Ab Cx during virus infection promote their expansion and resulted in exacerbated joint inflammation." (PMID 27886209, 2016). "This circuit of interferon-mediated Blimp-1 induction is also operational during chronic virus infection and can occur independently of IL-2 signaling." (PMID 27732671, 2016). "It has been reported that CypA is involved in T cell activation and in the IFN-I or IL-2 responses during virus infections." (PMID 26090438, 2015). "Inhibition of mTOR allowed for the differentiation of Tfh cells in the absence of TGF-βR signaling, suggesting that TGF-β insulates Tfh progenitor cells from IL-2-delivered mTOR signals, thereby promoting Tfh differentiation during acute viral infection." (PMID 25569154, 2015). "Here, we describe a new suppressive mechanism of Tregs on NK cell functions during an acute viral infection that is dependent on IL-2 availability or IL-2 consumption by Tregs." (PMID 26220086, 2015). "Multifunctional T cells simultaneously secreting IFN-γ, TNF-α, and IL-2 play a critical role in the control of chronic bacterial and viral infections." (PMID 26339657, 2015). "Single IFN-γ+ CD4+ T cells are associated with viral primary infection with high viral load, while chronic viral infection is related to single IL-2+ or IL-2+IFN-γ+ CD4+ T cell responses." (PMID 25822536, 2015). "The significant elevation of IL-2 (P<0.05) in intestines of infected groups at 4 and 7 days, suggests proliferation of lymphocytes in response to viral infection." (PMID 26659460, 2015). "After pdmH1N1 virus infection, cigarette smoke exposed mice had significantly higher production of IL-1α, IL-1β, IL-2, IFN-γ, KC, RANTES on day 3; IL-5, IL-10 and MIP-1α both on day 1 and day 3 in the lungs than the control mice." (PMID 24465940, 2014).
viral infection (continued). "In particular, the important role of the immune defence of the organism, especially cellular immunity and cytokine production of Th1-type IFN-γ and IL-2, is to execute control over the viral infection and tumor growth." (PMID 24386936, 2014). "IL-2 and IL-15 are structurally homologous to Th1 or Th1 related cytokines produced by mononuclear phagocytes and other cell types in response to viral infection." (PMID 24358317, 2013). "Viral infections are generally associated with the differentiation of IFNγ-, TNFα-, and IL-2-producing Th1 cells, driven by Type I IFN, IL-12, and IFNγ production provided by innate immune cells during viral infections." (PMID 23717308, 2013). "The serum IL-2 levels were detectable in a majority of control subjects (9 of 10; 90%) and patients with a viral infection (20 of 26; 76.9%), whereas all patients with the community-acquired bacterial infections had detectable levels (21 of 21; 100%)." (PMID 23690657, 2013). "For example IL-2 or type I IFN can enhance or inhibit T cell responses depending on the time-point after virus infection." (PMID 23738889, 2013). "Cytokines and chemokines that showed limited response in mice with any viral infection included Eotaxin, GM-CSF, IL-1α, M-CSF, IL-2, IL-3, IL-4, IL-5, IL-7, IL-9, IL-12p40, IL-13, IL-15, IL-17, MIP2, LIX, MIP1β, RANTES, IL-12p70, and VEGF (data not shown)." (PMID 23441208, 2013). "Elevated IFN-γ expression is an important immunological marker in the pathogenesis of HAM/TSP, and CD8+ T cell dysregulation was mediated by various factors, including virus infection, enhanced IL-2/IL-15, and expression of cellular molecules." (PMID 22335964, 2012). "Inasmuch as antigen presentation and cellular effector activity during a viral infection are regulated by cytokines, we evaluated the levels of serum IL-2, IL- 4, IL-6, IL-10, TNFα and IFNγ from LSIL patients and normal controls." (PMID 22642942, 2012). "It was reported that the levels of plasma sPLA2-IIa are elevated with bacterial and viral infection or IL-2 infusion and in coronary heart disease." (PMID 22151235, 2011). "Cell proliferation, activation of ERK1/2 and NF-κB, and secretion of IL-2 observed after PBj-wt virus infection in vitro seem to be mediated by interplay of Nef with the mitogenic signaling cascade involving the D-D-X-X-X-E motif." (PMID 21366921, 2011). "These cytokines which mainly included IL2, IL1, CXCL10 and RANTES were reported to be involved in cytokine-storm in response to viral infection in humans and thus associated with H5N1 virulence." (PMID 20828378, 2010). "As expected, CD4+ T-cells stimulated with PHA/IL-2 were highly susceptible to infection by the HSA reporter virus and the virus infection was strongly diminished in the presence of AZT." (PMID 19300495, 2009). "iii) Uupregulation of costimulatory molecules and MHC class I expression upon virus infection on NSPCs allows these cells to effectively costimulate T cells and also trigger their proliferation (via IL-2 production)." (PMID 19956550, 2009). "Previous studies showed the potential of the IL-2 gene as a molecular adjuvant, which appear promising for protective immunity against virus infection." (PMID 18940009, 2008). "By the same token, Tfh and Tfr differentiation is elevated in viral infections after IL-2 blockade." (PMID 40710339, 2025). "Furthermore, an increase in IL-2 levels promotes lymphocyte growth, proliferation, and differentiation, playing an essential role in the body’s immune response to viral infections." (PMID 37741960, 2023). "The ability of IL-2 to act on various cell populations may promote inflammatory reactions changes in IL-2 sensitivity during virus infection." (PMID 37848986, 2023). "In general, recombinant human IL-2 in immunorehabilitation of patients with post-COVID syndrome allowed significantly stimulation of NK cell functional potential, which is undoubtedly crucial for preventing viral infections and cancer immunosurveillance." (PMID 37111294, 2023).
viral infection (continued). "Moreover, HPV vaccines have been associated with increased levels of cytokines (IL-2, IL-6, IL-1α, and IL-1β) and with the induction of IFN-γ-producing CD4+ and CD8+ T-lymphocytes, cytotoxic cells that clear viral infections." (PMID 38068369, 2023). "Indeed, other studies have demonstrated that IL-2 signaling is essential for the development of robust secondary memory CD8+ T cell responses during viral infection." (PMID 36618376, 2022). "Adaptative immune responses may influence the risk of viral infections in newborns as their CD4+ T cells have delayed synthesis of IFNγ and IL-2 in presence of viral infections." (PMID 36482106, 2022). "In women, in the case of viral infection and further cytokine stimulation (e.g., IL-2), the cytotoxicity of dNK cells may be restored, and it is suggested that these lymphocytes might be important for fighting virus-infected cells." (PMID 36496894, 2022). "The IL-2 feature to promote memory cells when is present in low level could be useful to rescue viral-specific CD8 T cells during persistent viral infections." (PMID 33802622, 2021). "A system-wide analysis of the immune response to the rVSV-ZEBOV Ebola vaccine suggested negative regulation by inflammatory monocytes; additionally, IL-10 blockade restored antigen-specific T cell–derived IL-2–dependent activation of NK cells in other viral infection models." (PMID 32315287, 2020). "Adjuvant effects following IL-2 administration observed during systemic viral infection support that memory CD4 T cell-derived IL-2 may have similar proinflammatory effects in this setting." (PMID 31412088, 2019). "Indeed, this pattern was notably characterized by the high induction of interleukin 2 (IL-2) and interferon gamma-induced protein 10 (IP-10) in the context of all viral infections studied." (PMID 31391513, 2019). "For instance, NKp30 and NKp44 are highly induced on Vδ1+T cells after continued activation by γδTCR stimulation in the presence of IL-2 or IL-15, and the inducible NCRs endows Vδ1+T cells with enhanced cytotoxicity against leukemia cells and increased ability to control of virus infection." (PMID 30930903, 2019). "Likewise, in this study we showed that HIV-1 infection suppresses IL-2 through let-7i, which greatly impaired the protective effect against viral infection- and activation-induced apoptosis of the peripheral blood CD4+ T cells by IL-2." (PMID 27145859, 2016). "Changes in IL-2 sensitivity during active virus infection could change the responsive pattern towards the IL-2 Ab Cx, resulting in the expansion of pro-inflammatory rather than anti-inflammatory responses." (PMID 27886209, 2016). "Thus, IL-2 Ab Cx has different effects on the T cell populations in the two compartments during an active virus infection." (PMID 27886209, 2016). "Thus, Treg cells appear to play a central role in effector CD4 T cell fates during viral infection, likely by controlling the local bioavailability of both IL-2 and TGF-β." (PMID 25569154, 2015). "Thus, our previous data and the current results suggest an interplay of CD4+ helper T cells, Tregs and NK cells also in viral infections with IL-2 being the specific link between these cell populations." (PMID 26220086, 2015). "The specific stimulation of NK cells by IL-2 can result in improved control of viral infections." (PMID 26220086, 2015). "Thus, defined therapies with IL-2, which specifically improve NK cell responses, should be of interest to augment NK cell responses in viral infections or cancer." (PMID 26220086, 2015). "Antigen-specific T-cells secreting IL-2 with or without IFN-γ have been associated with containment (or resolution) of viral infections 18–20 and TB 21–23." (PMID 26417433, 2015).